THAP1 (THAP domain containing 1)
Description:
DNA-binding transcription regulator that regulates endothelial cell proliferation and G1/S cell-cycle progression. Specifically binds the 5'-[AT]NTNN[GT]GGCA[AGT]-3' core DNA sequence and acts by modulating expression of pRB-E2F cell-cycle target genes, including RRM1. Component of a THAP1/THAP3-HCFC1-OGT complex that is required for the regulation of the transcriptional activity of RRM1. May also have pro-apoptotic activity by potentiating both serum-withdrawal and TNF-induced apoptosis.
Synonyms: FLJ10477; 4833431A01Rik; DYT6
Tractability: PROTAC: ubiquitination databases record sites on it.
Gene: Protein-coding gene on chromosome 8 (42,836,674 to 42,843,338, reverse strand). Ensembl gene ENSG00000131931.
Subcellular location: Nucleus, nucleoplasm; Nucleus, PML body
Subcellular location (Human Protein Atlas): Nucleoplasm
Gene Ontology:
Molecular function: DNA-binding transcription repressor activity, RNA polymerase II-specific; identical protein binding; protein binding; protein homodimerization activity; RNA polymerase II cis-regulatory region sequence-specific DNA binding; sequence-specific DNA binding; zinc ion binding; DNA-binding transcription factor activity; DNA-binding transcription factor activity, RNA polymerase II-specific
Biological process: DNA-templated transcription; endothelial cell proliferation; negative regulation of transcription by RNA polymerase II; regulation of DNA-templated transcription; regulation of mitotic cell cycle; regulation of transcription by RNA polymerase II
Cellular component: nucleoplasm; nucleus; chromatin; PML body
Genetic constraint (gnomAD): Loss-of-function variants: 7 observed, 23.05 expected, observed/expected ratio (o/e) 0.3, 90% interval 0.17 to 0.57. The upper end of that interval is the gene's LOEUF score, 0.57, which puts it in group 2 of 6, group 1 being the genes least tolerant of losing a copy. Missense variants: 176 observed, 268.09 expected, observed/expected ratio (o/e) 0.66, 90% interval 0.58 to 0.74. Synonymous variants: 85 observed, 96.26 expected, observed/expected ratio (o/e) 0.88, 90% interval 0.74 to 1.06.
Homologues: Orthologues: chimpanzee THAP1 (100% identical), macaque THAP1 (99% identical), pig THAP1 (98% identical), guinea pig THAP1 (95% identical), mouse Thap1 (92% identical), rabbit THAP1 (92% identical), dog THAP1 (87% identical), rat Thap1 (85% identical), tropical clawed frog thap1 (56% identical), Drosophila melanogaster CG13894 (13% identical). Paralogues in human: THAP2 (32% identical), THAP3 (27% identical), THAP7 (23% identical), THAP8 (23% identical), THAP6 (12% identical), ARL14EP (12% identical), ARL14EPL (9% identical).
Diseases named in the same sentence as THAP1 in open-access papers:
THAP1 is named in the same sentence as 35 diseases in open-access papers, as found by Europe PMC text mining. Sharing a sentence is not in itself a finding about the gene and the disease. The quoted sentences say what the papers report.
Dystonia (73 papers, 2006 to 2026). An abnormally increased muscular tone that causes fixed abnormal postures. "Background and aims: DYT‐THAP1 dystonia is a rare genetic movement disorder caused by mutations in the THAP1 gene." (PMID 40542608, 2025). "Mutations in THAP1 can result in loss of function, leading to transcription dysregulation and dystonia-like conditions in humans." (PMID 39596884, 2024). "DYT-THAP1 is a frequent familial cause of dystonia due to mutations in the THAP1 gene (THAP domain-containing, apoptosis-associated protein 1)." (PMID 40735195, 2024). "Recent translational studies further provide mechanistic support for vulnerabilities of oligodendrocytes in dystonia caused by THAP1 mutations." (PMID 38557486, 2024). "Genetic variants in THAP1 are the second most common cause of isolated monogenic dystonia after TOR1A." (PMID 37637848, 2023). "To date, ∼100 missense, nonsense, and frameshift mutations in THAP1 have been described in dystonia patients of different ethnicities." (PMID 38835919, 2022). "With the exception of one, all were reported within the non-dystonia cohort, suggesting known contribution of incomplete penetrance in some known dystonia causing genes, such as THAP1 (DYT6) and TOR1A (DYT1)." (PMID 35925398, 2022). "Diffusion tensor imaging and tractography demonstrated an abnormal structural integrity of the white matter not only in patients with TOR1A and THAP1-related dystonia but also in symptomatic carriers of variants in the yet unconfirmed COL6A3 gene." (PMID 33486625, 2021). "Autosomal dominant mutations in the GNAL gene cause primary torsion dystonia, typically with a craniocervical onset, although progression to other sites and generalized dystonia can occur, with a phenotype resembling THAP1-associated dystonia." (PMID 33488508, 2020). "Mutations in THAP1 (THAP domain-containing apoptosis-associated protein 1) are responsible for DYT6 dystonia." (PMID 32112337, 2020). "DYT-THAP1 dystonia (also known as DYT6 dystonia) is an isolated dystonia caused by dominant mutations in the THAP1 gene." (PMID 31817799, 2019). "Fourteen individuals, 9 females and 5 males, with dystonia and sequence variants in THAP1 were included." (PMID 31817799, 2019). "This lack of specificity stands in contrast with genetically based dystonias (such as mutations in Tor1A or Thap1), in which a predictable pattern of symptom site(s) is expected." (PMID 27171035, 2016). "In all our THAP1 mutation carriers (four probands and their three affected relatives) the first signs of dystonia occurred before the age of 23." (PMID 26087139, 2015). "Over 90 point mutations within all three THAP1 exons have been described in DYT6 dystonia patients of different ethnicities." (PMID 26087139, 2015). "In this study we investigated a cohort of Polish patients with idiopathic isolated dystonia to assess the prevalence of THAP1 mutations and to characterize their phenotype." (PMID 26087139, 2015). "In all symptomatic THAP1 mutation carriers (four probands and their three affected relatives) the first signs of dystonia occurred before the age of 23." (PMID 26087139, 2015). "Among the known genetic causes of adult-onset primary dystonia, THAP1 dystonia appears to be associated with the most diverse ages of onset and anatomical distributions." (PMID 24936516, 2014). "A number of different mutation types and locations in the THAP1 gene have been associated with a range of severity and dystonia phenotypes, but, as yet, it has been difficult to identify clear genotype phenotype patterns." (PMID 22903657, 2012). "Here, we screened the THAP1 gene in a further series of dystonia cases and evaluated the mutation pathogenicity in this series as well as previously reported mutations to investigate possible phenotype-genotype correlations." (PMID 22903657, 2012).
Dystonia (continued). "Similarly, proper KMT2B functioning is essential for adequate expression of other dystonia-linked genes, such as THAP1 and TOR1A, which were reported to be downregulated in fibroblasts derived from patients with KMT2B pathogenic variants." (PMID 41518464, 2026). "Overall, these data identify THAP1 as a regulator of proteasome function and suggest that aberrant proteostasis could be a factor underlying the pathogenesis of THAP1 dystonias." (PMID 39929834, 2025). "Additionally, laryngeal dystonia frequently emerges early in genetic forms of dystonia, such as DYT6, THAP1-associated dystonia, often preceding other motor symptoms." (PMID 40672157, 2025). "Finally, we leveraged our functional reporter assay to perform a deep mutational scan of THAP1, quantifying the activity of thousands of single amino acid variants to define the landscape of THAP1 mutations in dystonia." (PMID 39929834, 2025). "It is believed that DYT6 dystonia results from a loss of THAP1 function, but the specific target gene of THAP1 involved in this disorder remains unclear." (PMID 39952963, 2025). "Here the authors characterise THAP1 as a transcriptional activator of PSMB5, suggesting that proteasome dysfunction might underlie the pathogenesis of THAP1 dystonia." (PMID 39929834, 2025). "Many of the THAP1 mutations identified in dystonia patients remain of uncertain significance." (PMID 39929834, 2025). "Finally, we generated Thap1 C54Y mutant knock-in mice to examine the effects of the dystonia-associated THAP1 mutation on proteasome regulation in vivo." (PMID 39952963, 2025). "The YY1 gene encodes the zinc-finger TF protein yin and yang 1 that interacts with the dystonia-associated gene THAP1 and activates the myelination gene expression program centered on the TF EGR2, thus highlighting the crucial role of YY1 in central nervous system myelination." (PMID 38042508, 2024). "THAP1 mutation dystonia is a known genetic cause of generalized dystonia." (PMID 40735195, 2024). "A systems biology approach that not only focuses on a single isolated component of the regulatory mechanisms may help to shed further light on dysregulated pathways underlying THAP1 dystonia." (PMID 38835919, 2022). "Pathogenic variants in THAP1 can cause dystonia with a penetrance of about 50 %." (PMID 38835919, 2022). "Mean age of onset for THAP1-associated dystonia is 16.8 years and ranges from 3 to over 60 years." (PMID 24936516, 2014). "Moreover, other dystonia-associated proteins including THAP1, TAF1, ATM, and Gα(olf), contribute to the G1/S checkpoint pathway." (PMID 24936516, 2014). "In other THAP1 screening series, this variant was reported in 3/455 subjects with primary dystonia and 1/185 controls, 1/567 dystonia subjects and 1/365 controls, 0/109 dystonia subjects and 1/185 controls." (PMID 24936516, 2014). "Therefore, we screened the THAP1 gene in a further series of dystonia cases from the United Kingdom and performed a meta-analysis of published cases to investigate a possible genotype/phenotype in THAP1-associated dystonia." (PMID 22903657, 2012). "Furthermore, by exploring the impact of single amino acid substitutions on THAP1 activity, studies showed that dystonia-related THAP1 variants produced a similar effect, providing a mechanistic link between THAP1 dysfunction and impaired proteasomal regulation." (PMID 41518464, 2026). "However, as the critical targets of THAP1 are poorly characterized, it remains unclear how the THAP1 mutations observed in dystonia patients result in disease." (PMID 39929834, 2025). "Moreover, it was found that wild-type THAP1 regulates genes involved in cell growth and proliferation in neuronal cells, while mutant THAP1 leads to the dysregulation of genes related to synaptic function, a process that has been reported as a pathogenic mechanism of other subtypes of dystonia." (PMID 38835919, 2022).
Dystonia (continued). "However, THAP1 downstream targets in neurons, the mechanism via which THAP1 mutations cause disease, and the disease mechanism underlying isolated dystonia, in general, are all largely unknown." (PMID 38835919, 2022). "However, further molecular and cellular functions as results of mutations in THAP1 causing dystonia remain largely unknown." (PMID 34095114, 2021). "However, THAP1 downstream targets in neurons, and the mechanism via which it causes dystonia are largely unknown." (PMID 29364887, 2018). "Thus, Thap1 appears to regulate cell cycle proteins and apoptosis, and of note, dysregulation of transcription and cell cycle proteins is associated with multiple genes, which when mutated, result in dystonia." (PMID 25231164, 2014). "Thus, one possible mechanism by which mutations in THAP1 might cause dystonia is by dysregulated transcription of key genes." (PMID 23775978, 2013). "In DYT6 (THAP1) dystonia, early laryngeal involvement is typical and often dominates the initial phenotype." (PMID 40672157, 2025). "We also identified a pathogenic THAP1 variant (p.Lys73Thr) in an individual and her mother, both diagnosed with PD and slight foot OFF-dystonia." (PMID 40672488, 2025). "The study assessed twelve participants using movement disorder specialist ratings of videotapes from patients with genetically determined dystonia (Tor1A and THAP1) who underwent GPi DBS." (PMID 38439837, 2024). "In the striatal MSA-P MSNs, we found a significant reduction in the expression of the GABAA receptor subunit α2, as was also observed recently in the MSNs of THAP1 dystonia patients." (PMID 36672158, 2023). "We also noted that three of the genes identified as chordoma dependency genes (THAP1, SLC2A1, and PRKRA) are causative for dystonia, a neurological condition characterized by involuntary muscle contractions." (PMID 37024492, 2023). "Due to uncertainties regarding the efficacy of GPi DBS in THAP1 dystonia, alternative targets for deep brain stimulation are being investigated, such as the ventral lateral anterior thalamic nucleus." (PMID 38027472, 2023). "THAP1-linked dystonia, previously referred to as DYT6 dystonia, is characterized by early-onset dystonia with prominent craniocervical and upper limb muscle involvement." (PMID 38835919, 2022). "Initial attempts to understand the role of THAP1 in transcriptional regulation were carried out before establishing the disease link to dystonia." (PMID 38835919, 2022). "The results of the 13 patients who underwent genetic testing were as follows: 10 patients with idiopathic isolated dystonia, 2 patients with TOR1A (DYT1)-positive isolated dystonia, and 1 patient with THAP1 (DYT6)-positive isolated dystonia." (PMID 33716933, 2021). "Among the genetic primary dystonias, craniocervical dystonia has been mainly described in the context of DYT6 caused by THAP1 (thanatos-associated protein 1) gene mutations." (PMID 24442708, 2014). "Herein, we present the results of a larger definitive case–control study of THAP1 c.71+9C>A in 1672 subjects with primary, mainly adult-onset, dystonia and 1574 neurologically normal Caucasian controls." (PMID 24936516, 2014). "As it pertains to dystonia, the key cell type of interest for Thap1 function is of course the neuron, where few observations have been reported." (PMID 25231164, 2014). "On the other hand, THAP1- and KMT2B-related disorders represent two prominent examples associated with transcriptional dysregulation that often feature isolated or seemingly isolated dystonia." (PMID 41518464, 2026). "For six variants, segregation analysis revealed that the identified variant co‐segregated with the dystonia phenotype in the affected families, supporting its pathogenic role (EIF2AK2:p.Pro31Ser, EIF2AK2:p.Gly130Arg, THAP1:p.Ser51Arg, GCH1:p.Glu61*, SGCE:p.Met174Lys, SGCE:c.233‐1G>A:p.)?" (PMID 40533913, 2025). "Nevertheless, it remains unclear which target gene of THAP1 is responsible for the pathogenesis of DYT6 dystonia." (PMID 39952963, 2025).
Dystonia (continued). "The majority (n=43) were carriers of heterozygous variants in genes linked to dominantly inherited dystonia genes (ATP1A3, GCH1, SGCE, KMT2B, THAP1, TOR1A, and VPS16), while only one carrier of a homozygous PLA2G6 variant and one of compound-heterozygous PTS variants were identified." (PMID 40672488, 2025). "In addition, dysregulation of the integrated stress response has been observed in several monogenic forms of dystonia, including those associated with variants in TOR1A, THAP1, PRKRA, EIF2AK2, and SGCE genes, suggesting a converging pathogenic mechanism." (PMID 40724495, 2025). "Altogether, these data identify THAP1 as a critical regulator of proteasome function and suggest that aberrant proteostasis may contribute to the pathogenesis of THAP1 dystonia." (PMID 39929834, 2025). "The THAP1 gene encodes a ubiquitously expressed transcription factor consisting of 213 amino acids and is putatively regulating the expression of various target genes, including TOR1A, the gene mutated in another form of dystonia, and THAP1 itself." (PMID 38835919, 2022). "Further, genetically engineered mice with heterozygote Thap1 mutations display structural abnormalities of the deep cerebellar nuclei and deficits on motor tasks without overt dystonia." (PMID 34095114, 2021). "Reports of dystonia patients with homozygous THAP1 mutations with non-manifesting heterozygous parents highlight dosage dependent effects of THAP1 mutations." (PMID 29364887, 2018). "Mutations in THAP1 [THAP (Thanatos-associated protein) domain containing, apoptosis associated protein 1], a ubiquitously expressed transcription factor with DNA binding and protein-interaction domains, cause dystonia, DYT6." (PMID 29364887, 2018). "Genetically engineered mice with heterozygote Thap1 mutations, either C54Y or ΔExon2, display structural abnormalities of the deep cerebellar nuclei and deficits on motor tasks without overt dystonia." (PMID 29364887, 2018). "RNA-Seq was performed in two brain regions, striatum and cerebellum, consistently implicated in dystonia pathogenesis, and at a developmental time point when Thap1 levels and transcriptional abnormalities peak, supporting the notion that dystonia is a developmental disorder." (PMID 29364887, 2018). "Our unbiased transcriptomics approach showed that Thap1 mutants revealed multiple signaling pathways involved in neuronal plasticity, axonal guidance, and oxidative stress response, which are also present in other forms of dystonia, particularly DYT1." (PMID 29364887, 2018). "Familial-isolated dystonias are predominantly inherited as incompletely penetrant autosomal dominant traits most frequently related to the DYT1 or DYT6 loci with mutations in TOR1A or THAP1, respectively." (PMID 29110692, 2017). "Another possibility is that the THAP1 mutations, albeit associated with dystonia, are not sufficient to cause the disease." (PMID 26087139, 2015). "However, the role of Thap1 as a major genetic modifier in DYT1-dystonia has been recently questioned." (PMID 23596437, 2013). "THAP1 mutations are an important cause of dystonia, but, as yet, no clear genotype-phenotype correlations have been identified." (PMID 22903657, 2012). "Botulinum toxin injections that are clinically beneficial for mitigating lingual dystonia symptoms should be utilized to address symptoms of THAP1 mutation dystonia that may not be amenable to other therapies, such as the DBS." (PMID 40735195, 2024). "However, factors contributing to incomplete penetrance and variable expressivity as well as the disease mechanism of THAP1 dystonia are largely unknown." (PMID 38835919, 2022). "Mutations in some dystonia genes, such as THAP1 (DYT6), can cause both focal/segmental and generalized forms of the disease, while others (e.g., TH or GCH1) may even give rise to both isolated and combined dystonias." (PMID 28138320, 2016).